TRIM52 (tripartite motif containing 52)
Diseases named in the same sentence as TRIM52 in open-access papers (continued):
Sharing a sentence is not in itself a finding about the gene and the disease.
tumor (5 papers, 2018 to 2024). "TRIM52 expression was closely related with tumor size (p = 0.0376), tumor stage (p = 0.0227) and overall survival (p = 0.0177)." (PMID 30918473, 2019). "In line with this, cells with high TRIM52-targeting shRNA expression are preferentially lost during tumor formation, indicating that TRIM52 ablation confers a selective disadvantage in vivo." (PMID 29568378, 2018). "It indicated that knockdown of TRIM52 inhibited tumor cell growth and proliferation, but promoted cell apoptosis." (PMID 30185771, 2018). "We assessed the effect of TRIM52 in tumor formation in athymic nude mice by subcutaneously injecting SKOV3 cells." (PMID 30185771, 2018). "The results showed that positive staining cells decreased in the tumor treated by TRIM52 knockdown compared with NC." (PMID 30185771, 2018). "The nude mice study further confirmed that knockdown of TRIM52 blocked tumor growth, inhibited cell proliferation, and promoted cell apoptosis." (PMID 30185771, 2018). "The study of tumorigenesis in vivo also confirmed that blocking TRIM52 inhibited tumor growth and cell proliferation, but induced cell apoptosis." (PMID 30185771, 2018). "Together, these results show that TRIM52 ablation reduces tumor growth in vivo, which is consistent with our cell culture results." (PMID 29568378, 2018). "The tumor slide showed less positive green fluorescence cells in the group treated by TRIM52-knockdown SKOV3 cells compared with NC, which implied that TRIM52 knockdown downregulated TRIM52 and NF-kB P65 expressions." (PMID 30185771, 2018). "TRIM52 was significantly up-regulated in the HCC tissues in comparison with the adjacent non-tumor hepatic tissues." (PMID 29898761, 2018). "Immunofluorescence staining was employed to evaluate TRIM52 and NF-kB P65 expressions in mice tumor." (PMID 30185771, 2018). "In contrast, the Fluc signal from TRIM52-targeted tumors was significantly lower at these time points (∼4-fold), indicating that TRIM52-knockdown diminishes tumor growth." (PMID 29568378, 2018). "Western blot confirmed that TRIM52 and NF-kB P65 protein levels decreased in TRIM52-knockdown tumor." (PMID 30185771, 2018). "On Day 33 after cell inoculation, the weight of the xenograft formed by RNAi#1 cells was significantly lighter than that of NC cells, which suggested that knockdown of TRIM52 could inhibit tumor growth in nude mice." (PMID 30918473, 2019). "TRIM52 expression was correlated with tumor size, TNM stages and tumor number." (PMID 29898761, 2018). "TRIM52 expression in tumor tissue was significantly higher compared with normal tissue (P < 0.01)." (PMID 30185771, 2018). "In line with the recent findings, our results also demonstrated TRIM52 up-regulation in the HCC tissues compared with the adjacent non-tumor hepatic tissues, and in HCC cell lines, including high metastatic MHCC-97H and low metastatic MHCC-97L, compared with normal human liver cell line LO2." (PMID 29898761, 2018). "Lastly, we determined by flow cytometry whether TRIM52-targeted tumors had reduced GFP -and thus shRNA- expression, indicative of out-selection of tumor cells with the strongest TRIM52 knockdown as seen in cell culture." (PMID 29568378, 2018). "Next, we investigated whether TRIM52 is required for optimal tumor growth in a U87MG xenograft mouse model." (PMID 29568378, 2018). "In contrast to non-tumor tissues, CRC tissues show higher levels of TRIM52 expression, and elevated TRIM52 levels are significantly correlated with the proliferation, migration and invasion of CRC cells." (PMID 38678238, 2024). "In present study, we provided new evidence that TRIM52 expression was elevated in CRC tissues and cell lines, and that TRIM52 expression was significantly correlated with tumor size, tumor stage and overall survival of CRC patients." (PMID 30918473, 2019).
tumor (continued). "TRIM52 expression was correlated with tumor size, TNM stages and tumor number, but uncorrelated with age, sex, recurrence, pathologic stages, differentiation, lung metastasis, HBsAg and HBV infection." (PMID 29898761, 2018). "TRIM52 Immunohistochemistry (IHC) assays based on TMA showed obviously positive staining in cell nucleus and cytoplasm of the tumor samples (Fig. 1dii-v)." (PMID 30185771, 2018). "As shown in Fig. 6ai-iv, the size of the tumor was much smaller in the mice group injected with SKOV3 cells treated with TRIM52-Ri3 lentivirus than those of nontargeted RNA control and noninfected cells group." (PMID 30185771, 2018). "TRIM52 mRNA level in tumor tissue was higher than that of paired noncancerous tissue." (PMID 30185771, 2018). "IHC analysis on tissue microarrays containing 87 human HCC and adjacent non-tumor hepatic tissue samples found that TRIM52 was significantly up-regulated in the HCC tissues in comparison with the adjacent non-tumor hepatic tissues, specially between groups –, + and groups ++, +++." (PMID 29898761, 2018).
infection (4 papers, 2018 to 2025). The state of being infected such as from the introduction of a foreign agent such as serum, vaccine, antigenic substance or organism. "To screen for factors that induce the degradation of TRIM52, we transduced a lentiviral sgRNA-encoding library into our reporter cell line at a low multiplicity of infection to ensure targeting of only one gene per cell." (PMID 40274822, 2025). "Based on this observation we hypothesised that TRIM52 could be induced during the complex cellular stress caused by such infection." (PMID 31133683, 2019). "But additional PDTC decreased the OD value in TRIM52-overexpression HO8910 cells at 24 h, 48 h, and 72 h after infection." (PMID 30185771, 2018). "Notably, multiple antiviral proteins were also dramatically decreased in PAMs during the PRRSV-ADE infection, including ISG15, ISG20, IFIT1 (ISG56), IFIT2 (ISG54), IFIT3 (ISG60), IFIT5 (ISG58), OAS1, Mx1, RSAD2, TRIM22, TRIM25 and TRIM34, except for TRIM52." (PMID 36680075, 2022).
colorectal (1 paper, 2019). "Nevertheless, the roles and mechanisms of TRIM52 in colorectal carcinogenesis have not been investigated." (PMID 30918473, 2019).
TRIM52 also shares sentences with these, for which no sentence is quoted: breast carcinoma (1 paper); glioma (1); injury (1); lung carcinoma (1); Sepsis (1).